PXDN (peroxidasin)
Diseases named in the same sentence as PXDN in open-access papers (continued):
Sharing a sentence is not in itself a finding about the gene and the disease.
nasopharyngeal carcinoma (2 papers, 2024 to 2025). A carcinoma arising from the nasopharyngeal epithelium. "Taking nasopharyngeal carcinoma as an example, in vitro experiments were conducted to explore the biological functions of PXDN." (PMID 39399179, 2024). "To further explore the function of PXDN in tumors, we used nasopharyngeal carcinoma as our research object because no relevant research on NPC has been reported." (PMID 39399179, 2024).
renal fibrosis (2 papers, 2017 to 2021). A final common manifestation of a wide variety of chronic kidney diseases characterized by glomerulosclerosis and tubulointerstitial fibrosis. "Furthermore, the expression of peroxidasin (a synonym for VPO1) is increased in a mouse model of renal fibrosis induced by unilateral ligation of the ureter." (PMID 32813143, 2021). "It is possible that Br- mediates the assembly of type IV collagen by regulating the peroxidasin activity, which could exacerbate the AS pathologies including renal fibrosis." (PMID 28873450, 2017).
sarcoma (2 papers, 2022 to 2023). A usually aggressive malignant neoplasm of the soft tissue or bone. "High expression of PXDN has also been reported to be associated with reduced overall survival in ovarian, bladder, gastric and uterine cancers as well as sarcomas." (PMID 37801286, 2023).
anaplastic thyroid cancer (1 paper, 2023). "PXDN is part of a four gene signature that showed diagnostic potential in anaplastic thyroid cancer for molecular targeted therapy and immunotherapy." (PMID 37801286, 2023).
bacterial pneumonia (1 paper, 2018). Acute infection of the lung parenchyma caused by bacteria (e.g., Streptococcus pneumoniae, Haemophilus influenzae, Chlamydia pneumoniae, Mycoplasma pneumoniae, and Legionella pneumophila). "Together, these studies provide compelling data to support a critical host defense function of PXDN, specifically against GN bacterial pneumonia." (PMID 29775486, 2018). "To determine whether PXDN mediates critical host defense functions in vivo, we employed a murine model of GN bacterial pneumonia in wild-type and PXDN mutant mice (PXDNmhdakta048)." (PMID 29775486, 2018).
cervical cancer (1 paper, 2020). A primary or metastatic malignant neoplasm involving the cervix. "However, PXDN is reported to be negatively regulated by Snail activation during the EMT in cervical cancer cells." (PMID 32751434, 2020).
childhood glaucoma (1 paper, 2025). "Variants in COL4A1 and PXDN, which are both basement membrane components, have been identified in patients with anterior segment dysgeneses associated with childhood glaucoma, although only the c.2159G>A p.(Gly720Asp) has been reported in more than one family." (PMID 41011222, 2025).
cholangiocarcinoma (1 paper, 2022). A carcinoma that arises from the intrahepatic biliary tree (intrahepatic cholangiocarcinoma) or from the junction, or adjacent to the junction, of the right and left hepatic ducts (hilar cholangiocarcinoma). "With the exception of four tumors (ACC, GBM, Pheochromocytoma and Paraganglioma (PCPG), and Cholangiocarcinoma (CHOL)), there was an evident negative correlation between the PXDN expression and the methylation level in all other tumors." (PMID 35982948, 2022).
chronic pancreatitis (1 paper, 2024). A chronic inflammatory process causing damage and fibrosis of the pancreatic parenchyma. "Furthermore, the investigators found that LRFN5 and PXDN did not exhibit significant methylation frequency in patients with chronic pancreatitis (CP) compared to healthy individuals, providing better distinction than the panel of ADAMTS1 and BNC1 alone." (PMID 38672671, 2024).
colon adenocarcinoma (1 paper, 2022). "With the exception of KIRP, there was a higher PXDN expression in BLCA, Colon adenocarcinoma (COAD), Testicular Germ Cell Tumors (TGCT), UCEC, and UVM that often implied a higher staging, and the p-values were statistically significant." (PMID 35982948, 2022).
developmental disability (1 paper, 2019). Disorders in which there is a delay in development based on that expected for a given age level or stage of development. "From this study, PXDN deficiency is presumed to be associated with developmental disability in eyes, as they lack the stability of the Col IV network because of the deficiency of sulfilimine crosslinks." (PMID 31817535, 2019).
developmental eye defects (1 paper, 2016). "The defective peroxidasin was described to affect the structural integrity of the ocular basement membrane, causing damage to the anterior segment of the eye and leading to developmental eye defects." (PMID 27409795, 2016).
embryonic carcinoma (1 paper, 2021). "We found the double epitope-labeled PXDN to be fully functional, as we could restore the missing collagen IV crosslinking in PXDN-deficient mouse embryonic carcinoma (PFHR-9) cells." (PMID 34679700, 2021).
fungal infection (1 paper, 2021). "Other immune-related genes were mapped to the database, but most of the genes were not strongly affected by the fungal infection (|FC| < 1): D. melanogaster cactus, pelle and caspar genes, and peroxidasin, thioredoxin peroxidase, and other serpin genes." (PMID 34093222, 2021).
hepatocellular carcinoma (1 paper, 2016). A malignant tumor that arises from hepatocytes. "Six genes carrying DNVs were associated with human developmental disorders involving epithelial, connective or bone morphologies (PXDN, RTEL1, ANKRD11, MAP2K1, CYLD, ACAN) and four linked with cholangio- and hepatocellular carcinomas (PIK3CA, TLN1 CYLD, MAP2K1)." (PMID 27955658, 2016).
Insulin resistance (1 paper, 2021). Increased resistance towards insulin, that is, diminished effectiveness of insulin in reducing blood glucose levels. "In addition, si-PXDN alleviated PA-induced insulin resistance in the form of increased glucose consumption." (PMID 33903591, 2021).
Jacobsen syndrome (1 paper, 2024). A multiple congenital anomaly/intellectual disability contiguous gene syndrome caused by partial deletion of the long arm of chromosome 11. "Most importantly, the use of WES has allowed us to both assess variants in known ASD genes (i.e., CYP1B1, ITPR1, MAB21L1, PXDN, and PITX2) and to identify rarer phenotypes (i.e., MIDAS, oculogastrointestinal-neurodevelopmental syndrome and Jacobsen syndrome)." (PMID 38459225, 2024).
lung adenocarcinoma (1 paper, 2023). A carcinoma that arises from the lung and is characterized by the presence of malignant glandular epithelial cells. "These proteins were up-regulated in lung tumour samples, and high PXDN and ADAMTS16 gene expression was associated with shorter survival of lung adenocarcinoma and squamous cell carcinoma patients, respectively." (PMID 37397358, 2023).
Lupus (1 paper, 2025). "Further links of C3-LHF1 to Lupus and particularly lupus nephritis also come with its physical association in plasma to peroxidasin, a protein suggested to be an autoepitope in lupus nephritis, or lupus-linked proteins such as RPL22, and WDR1." (PMID 41145914, 2025). "While our data found a classical engagement of C3 with C3 and C4, nidogen-1 (NID1), and plasminogen (PLG), C3-LHF1 also engaged with other lupus- and autoimmune-related proteins, such as WDR1, RPL22, and PXDN, supporting its mechanism of interacting with surface binders." (PMID 41145914, 2025).
mental disorder (1 paper, 2024). A disease that has its basis in the disruption of mental process. "To investigate potential specific links between ELA, PXDN DNA methylation and different mental disorders, we analyzed the distribution of cg10888111 methylation among the different cohorts (BPD, MDD and SAD) with respect to ELA." (PMID 39199364, 2024). "Providing a direct comparison of cg10888111 DNA methylation in blood in the context of ELA across three mental disorders, our results indicate the role of PXDN regulation in the response to ELA in the pathogenesis of mental disorders, especially MDD." (PMID 39199364, 2024). "However, based on previous findings, we hypothesize a contribution of the immune system’s response to ELA to an adult mental disorder (i.e., MDD) via PXDN regulation." (PMID 39199364, 2024).
metastatic cancers (1 paper, 2020). A carcinoma which has spread from the original site of growth to another anatomic site. "PXDN immunoreactivity was observed in 28.4% of non-metastatic cases, whereas 56.8% of metastatic cancers expressed PXDN." (PMID 32751434, 2020).
metastatic melanoma (1 paper, 2016). A melanoma that has spread from its primary site to another anatomic site. "PXDN expression was detected in 81% (50/62) of metastatic melanoma patient tumors." (PMID 27172792, 2016). "Our results show that PXDN, NTN4 and GLIS3are overexpressed in metastatic melanoma clinical specimens." (PMID 27172792, 2016).
neuroblastoma (1 paper, 2016). Neuroblastoma (NB) is the most common solid, extracranial childhood tumor. "Additional five mutated genes (LRRC17, PXDN, FZD1, ARHGEF10L, ATRX) were highly expressed in neuroblastoma and involved in cancer progression." (PMID 27009842, 2016). "Other five genes (LRRC17, PXDN, FZD1, ARHGEF10L, ATRX) resulted to be expressed in neuroblastoma and involved in cell migration and invasion." (PMID 27009842, 2016).
non-alcoholic fatty liver disease (1 paper, 2025). "Importantly, peroxidasin has been reported to be highly expressed in fibrotic contexts, including in murine models of kidney fibrosis and non-alcoholic fatty liver disease." (PMID 40654875, 2025).
rectal cancer (1 paper, 2025). A primary or metastatic malignant neoplasm that affects the rectum. "Unlike observations in rectal cancer, where PXDN downregulation occurred after preoperative radiotherapy, an irradiation dose-dependent induction of PXDN was identified in NPC." (PMID 41413560, 2025).
squamous cell carcinoma (1 paper, 2023). A carcinoma arising from squamous epithelial cells. "In contrast, there was no statistical association of expression of PXDN with survival of squamous cell carcinoma patients, whereas higher expression of ADAMTS16 was significantly associated with shorter survival of squamous cell carcinoma patients (HR = 1.72; 95% CI, 1.18–2.50; P = 0.0043)." (PMID 37397358, 2023).
uterine tumors (1 paper, 2024). "According to our analysis, the frequency of PXDN alteration (~13%) is the highest in uterine tumors with “mutation” as the primary type." (PMID 39399179, 2024).
tumor (30 papers, 2010 to 2026). "While PXDN dysregulation has been implicated in tumor progression, the molecular mechanisms governing its expression remain incompletely understood." (PMID 41413560, 2025). "Abnormal expression of PXDN in tumours has been linked to changes in cell viability, proliferation, migration, and invasion." (PMID 37801286, 2023). "Our results showed that the PXDN expression was positively correlated with tumor-associated fibroblast infiltration in almost all tumors, and this result was also consistent with that of previous findings." (PMID 35982948, 2022). "Further, we evaluated the association of PXDN expression with DNA methylation status, tumor mutation burden, and microsatellite instability." (PMID 35982948, 2022). "Although the PXDN protein is known to act as a tumor-promoting factor associated with the Warburg effect, its function and role in OSCC are poorly understood." (PMID 32751434, 2020). "Given the established association between ECM pathways and tumor metastasis, we hypothesized that PXDN may promote the development of NPC by facilitating ECM signal transduction." (PMID 41413560, 2025). "Taken together, these data suggest that high expression of PXDN in tumors may cause T-cell dysfunction in the tumor microenvironment, leading to T-cell exhaustion, promoting tumor immune escape, and promoting tumor progression." (PMID 39399179, 2024). "PXDN activity was shown to promote angiogenesis and PXDN expression is associated with an increased invasive potential of cancer cells, possibly due to the remodelling of the tumour ECM to promote a permissive environment for cell invasion and metastasis." (PMID 38275643, 2023). "Thus, it is likely that PXDN may be expressed by cancer-associated fibroblasts (CAFs) especially in tumours with a high degree of desmoplasia." (PMID 37801286, 2023). "Through temporal proteomic analysis of dysregulated ECM proteins, we identified PXDN as upregulated during early tumor development in mouse models." (PMID 42291185, 2026). "Reduction of CAF-derived PXDN in vivo slows tumor development, while pharmacological inhibition of extracellular peroxidases improves overall survival." (PMID 42291185, 2026). "Integrating differentially expressed genes (DEGs; tumor vs. normal tissue), DFS-associated prognostic genes from multiple cohorts, and hub genes from the magenta module, we identified PXDN as a key regulator." (PMID 41413560, 2025). "To assess the tumor-promoting role of PXDN in NPC in vivo, we employed subcutaneous xenograft and lung metastasis mouse models." (PMID 41413560, 2025). "Functional and mechanistic studies reveal that PXDN promotes tumour aggressiveness via ECM-mediated activation of the ITGB1/PI3K/AKT axis." (PMID 41413560, 2025). "To fully explore PXDN expression in different tumors, we further assessed the differences in PXDN expression between tumor and normal tissues using the GEPIA database." (PMID 39399179, 2024). "Molecular biology experiments validated the pro-tumor role of PXDN by promoting NPC cell proliferation and metastasis." (PMID 39399179, 2024). "Co-culture experiments confirmed that high PXDN expression potentially inhibited T-cell proliferation and anti-tumor immunity." (PMID 39399179, 2024). "We also assessed the relationship between PXDN expression and T-cell infiltration in the tumor microenvironment, which revealed that high PXDN expression inhibited T-cell anti-tumor immunity in NPC." (PMID 39399179, 2024). "A recent bioinformatics study highlighted the involvement of PXDN in the infiltration of fibroblasts and various immune cells, suggesting its potential as a promising target for tumor immunotherapy." (PMID 38389400, 2024). "PXDN dysregulation is observed in various cancers, influencing the tumor microenvironment and immune cell infiltration." (PMID 39401197, 2024). "In future, spatial proteomics studies would be highly beneficial in determining the spatial location of PXDN within tumours." (PMID 37801286, 2023).
tumor (continued). "Of the extracellular proteins we quantified as up-regulated in tumours, we selected peroxidasin and ADAMTS16 for further analysis." (PMID 37397358, 2023). "Peroxidasin is an enzyme with an emerging role in tumour progression and metastasis that is involved in extracellular matrix (ECM) remodelling and modulating the composition and organisation of the ECM." (PMID 37801286, 2023). "Expression of both PXDN (which encodes peroxidasin) and ADAMTS16 were significantly up-regulated in adenocarcinoma tumours compared to matched adjacent normal lung tissue (1.96-fold and 10.7-fold change in median expression, respectively)." (PMID 37397358, 2023). "According to the results of our analysis of the expression of PXDN in tumor tissues and corresponding normal tissues, significant differences were found in 31 tumor types." (PMID 35982948, 2022). "Based on the findings of the role of PXDN in the tumor microenvironment, we conducted an in depth investigation into the relationship between PXDN and specific immune cell infiltration." (PMID 35982948, 2022). "We subsequently analyzed the effect of the PXDN methylation level on tumor prognosis, and obtained Kaplan-Meier survival curves for different methylation levels in different tumors." (PMID 35982948, 2022). "Peroxidase (PXDN), a specific extracellular matrix (ECM)-associated protein, has been determined as a tumor indicator and therapeutic target in various tumors." (PMID 36118855, 2022). "PXDN is also involved in related pathways within the tumor microenvironment, including epithelial-mesenchymal transformation." (PMID 35982948, 2022). "Meanwhile, inhibiting the activity of PXDN abolishes the tumor-promoting effect of FPM, indicating the key impact of aberrant PXDN activity on the tumorigenic process." (PMID 35437145, 2022). "According to our results, PXDN plays a role through certain classical tumor pathways in most tumors, such as the “TNF BETA SIGNALING” or “PI3K AKT MTOR SINALING” pathways." (PMID 35982948, 2022). "The results of tissue microarray immunohistochemistry showed that the expression of PXDN was significantly correlated with tumor size and pathological grade." (PMID 35646692, 2022). "We further investigated the relationship between PXDN and the tumor microenvironment, including the stromal and immune microenvironments." (PMID 35982948, 2022). "With the exception of UCEC, in which the PXDN protein expression level of normal tissue was high, PXDN protein was highly expressed in the other six tumor types." (PMID 35982948, 2022). "PXDN, an adhesion molecule which is significantly increased in haze predisposed patient epithelia is involved in ECM formation and reported to promote tumor growth." (PMID 31740714, 2019). "Therefore, to better understand the tumor-promoting behavior and abnormal expression of PXDN, it is necessary to clarify the genetic alterations and copy number alterations in PXDN in different tumors." (PMID 39399179, 2024). "Thus, we further explored PXDN genetic alterations in human tumor samples in the cBiPortal for Cancer Genomics database." (PMID 39399179, 2024). "During cancer progression, the basement membrane is degraded, and proteins typically found in the basement membrane, including peroxidasin and collagen IV, can be found spread throughout the tumour microenvironment where they interact with cancer cells and alter cell behaviour." (PMID 37801286, 2023). "We also discussed the effect of PXDN expression on tumor stage." (PMID 35982948, 2022). "We then explored the possible PXDN action mechanisms within the tumor microenvironment." (PMID 35982948, 2022). "Although this result indicated that a high PXDN expression in tumor tissues was accompanied by the infiltration of large numbers of immune cells, the specific types of immune cells involved required specific tumor analysis." (PMID 35982948, 2022).